EIF2B2 (eukaryotic translation initiation factor 2B subunit beta)
Description:
Acts as a component of the translation initiation factor 2B (eIF2B) complex, which catalyzes the exchange of GDP for GTP on eukaryotic initiation factor 2 (eIF2) gamma subunit. Its guanine nucleotide exchange factor activity is repressed when bound to eIF2 complex phosphorylated on the alpha subunit, thereby limiting the amount of methionyl-initiator methionine tRNA available to the ribosome and consequently global translation is repressed.
Synonyms: EIF2B; EIF-2Bbeta; EIF2Bbeta; VWM2
Tractability: Small molecule: a structure with a bound ligand is known. Antibody: the Human Protein Atlas places it where antibodies can reach. PROTAC: ubiquitination databases record sites on it; its protein half-life has been measured.
Chemical probes: DNL343 (high quality)
Gene: Protein-coding gene on chromosome 14 (75,002,894 to 75,012,366, forward strand). Ensembl gene ENSG00000119718.
Subcellular location: Cytoplasm, cytosol
Subcellular location (Human Protein Atlas): Focal adhesion sites; Plasma membrane; Nucleoplasm
Pathways (Reactome):
Metabolism of proteins: Recycling of eIF2:GDP
Gene Ontology:
Molecular function: ATP binding; GTP binding; guanyl-nucleotide exchange factor activity; protein binding; translation initiation factor activity
Biological process: central nervous system development; cytoplasmic translational initiation; myelination; oligodendrocyte development; ovarian follicle development; positive regulation of translational initiation; T cell receptor signaling pathway; translational initiation; regulation of translational initiation; response to glucose; response to heat; response to peptide hormone; animal organ development
Cellular component: cytoplasm; eukaryotic translation initiation factor 2B complex; cytosol
Genetic constraint (gnomAD): Loss-of-function variants: 31 observed, 33.47 expected, observed/expected ratio (o/e) 0.93, 90% interval 0.69 to 1.25. The upper end of that interval is the gene's LOEUF score, 1.25, which puts it in group 5 of 6, group 1 being the genes least tolerant of losing a copy. Missense variants: 359 observed, 471.95 expected, observed/expected ratio (o/e) 0.76, 90% interval 0.7 to 0.83. Synonymous variants: 155 observed, 184.61 expected, observed/expected ratio (o/e) 0.84, 90% interval 0.74 to 0.96.
Gene-disease validity (ClinGen):
ClinGen rates the evidence that EIF2B2 causes each of these diseases.
leukoencephalopathy with vanishing white matter 2 (autosomal recessive): Definitive.
Homologues: Orthologues: chimpanzee EIF2B2 (99% identical), macaque EIF2B2 (99% identical), guinea pig EIF2B2 (96% identical), rabbit EIF2B2 (96% identical), dog EIF2B2 (95% identical), mouse Eif2b2 (94% identical), rat Eif2b2 (94% identical), pig EIF2B2 (82% identical), zebrafish eif2b2 (80% identical), tropical clawed frog eif2b2 (80% identical), Drosophila melanogaster eIF2Bbeta (47% identical), Caenorhabditis elegans eif-2Bbeta (27% identical). Paralogues in human: EIF2B4 (23% identical), EIF2B1 (19% identical), MRI1 (19% identical).
Diseases named in the same sentence as EIF2B2 in open-access papers:
EIF2B2 is named in the same sentence as 17 diseases in open-access papers, as found by Europe PMC text mining. Sharing a sentence is not in itself a finding about the gene and the disease. The quoted sentences say what the papers report.
Leukoencephalopathy (3 papers, 2018 to 2025). This term describes abnormality of the white matter of the cerebrum resulting from damage to the myelin sheaths of nerve cells. "Besides, the impairment of stress response by mutations in EIF2AK2 –which encodes a eiF2α kinase–and eiF2B genes–EIF2B1 and EIF2B2– leads to leukoencephalopathy, hereby suggesting the importance of the UPR in CNS structure." (PMID 39071803, 2024).
ovarioleukodystrophy (2 papers, 2004 to 2022). The "ovarioleukodystrophies" comprise a group of rare leukodystrophies associated with primary or premature ovarian failure. "Recently three of the five EIF2B genes (EIF2B2, 4 and 5) were reportedly involved in seven patients who presented with POF and white matter abnormalities on MRI (ovarioleukodystrophy)." (PMID 15507143, 2004).
asthenospermia (1 paper, 2023). "In human male asthenospermia, EIF2B2 (eukaryotic translation initiation factor 2B subunit beta) is important for sperm motility." (PMID 36766254, 2023).
coronary artery disease (1 paper, 2021). "Dynamic eQTL for EIF2B2 overlaps a coronary artery disease GWAS locus." (PMID 33554857, 2021).
Premature Ovarian Failure (1 paper, 2010). "In humans, mutations in these genes have been detected in females with POF (Premature Ovarian Failure) and it has been hypothesized that EIF2B2 dysfunction in humans may be related to increased apoptosis of ovarian follicles." (PMID 20122165, 2010).
neurological disease (1 paper, 2021). "VWM is a neurological disease caused by mutations in the eukaryotic translation initiation factor 2B (EIF2B) that produce bi-allelic pathogenic variants in one of five genes: EIF2B1, EIF2B2, EIF2B3, EIF2B4, or EIF2B5." (PMID 33800130, 2021).
EIF2B2 also shares sentences with these, for which no sentence is quoted: leukodystrophy (2 papers); memory impairment (2); cancer (1); Cerebroretinal vasculopathy (1); colon tumors (1); dementia (1); metachromatic leukodystrophy (1); Niemann-Pick disease (1); ovarian dysfunction (1); Vanishing White Matter disease (1); viral infections (1).